TNF (tumor necrosis factor)
Diseases named in the same sentence as TNF in open-access papers (continued):
Sharing a sentence is not in itself a finding about the gene and the disease.
depression (continued). "In addition, studies using animal models have indicated that TNFα inhibition improved depression-like behaviour." (PMID 39358787, 2024). "Additionally, chronic mild stress and other depression models have shown increased levels of pro-inflammatory cytokines like IL-1β, IL-6, TNF-α, and IL-17 in both animals and humans." (PMID 39335629, 2024). "Furthermore, severe anxiety and depression can also induce immune activation, leading to elevated levels of cytokines, including TNF-α, and the use of immunosuppressants such as interferon-α can alleviate these emotional disorders." (PMID 39295596, 2024). "Proinflammatory cytokines tumor necrosis factor α (TNF-α), interleukin-1 β (IL-1β), and interleukin-10 (IL-10) are elevated in major depressive disorder and HS, suggesting a possible pathophysiological process for increased inflammatory symptoms in comorbid patients." (PMID 39173146, 2024). "In prenatally stressed animals, increased levels of IL-1β and TNF-α might influence brain development and stress-related anxiety and depression-like behaviors." (PMID 39272253, 2024). "Inflammation, marked by elevated pro-inflammatory cytokines like IL-6, TNF-α, and C-reactive protein, is a shared mechanism between depression and dementia, contributing to neurodegeneration, hippocampal damage, and disrupted neuroplasticity, leading to cognitive impairments." (PMID 39429291, 2024). "Taken together, we hypothesized that TNF-α promoted depression-like behavior in CUMS mice by binding to TNFR1 to activate astrocytes, whereas Rho alleviated this process and thus exerted antidepressant effects." (PMID 38710713, 2024). "Furthermore, mangiferin downregulates the contents of IL-18, IL-1β, IL-6, and TNF-α in the hippocampus of the CUMS-induced depression mouse model by inhibiting the NLRP3/ASC/caspase-1 pathway." (PMID 38915473, 2024). "Based on these findings, we hypothesized that TNF-α might worsen depression by activating A1 astrocytes." (PMID 38710713, 2024). "Those with high levels of TNF but not IL6 or CRP were associated with a greater presence of depression." (PMID 38175420, 2024). "The mechanisms underlying anxiety and depression following TBI are currently unclear, but inflammation post-TBI is speculated to be a contributing factor, associated with elevated levels of TNF-α, IL-6, IFN-α, and CRP." (PMID 39554848, 2024). "Cytokines like IL-6 and TNF-α are involved in inflammation and immune responses, and their levels are frequently elevated in depressed patients, further supporting the link between inflammation and depression." (PMID 39329797, 2024). "Our results indicated that the levels of C3, TNF-α, and TNFR1 were increased in the CUMS mice, and TNF-α could activate primary astrocytes, suggesting that TNF-α may activate pro-inflammatory astrocytes by TNFR1 signaling pathways during depression." (PMID 38710713, 2024). "Surgical trauma could lead to the release of inflammatory mediators (e.g., TNF‐α and IL‐1, etc.)and ultimately produce postoperative pain, which was often correlated with anxiety, depression, sleep disturbances, and postoperative cognitive dysfunction." (PMID 38376027, 2024). "Furthermore, the direct infusion of pro-inflammatory cytokines such as IL-1β and TNF-α into the brain has been shown to induce depression-like behaviors in rodents." (PMID 39130643, 2024). "SSRIs have an immunomodulatory effect in patients with depression by significantly reducing the peripheral pro-inflammatory cytokine markers of IL-6 and TNF-α, which may contribute to ameliorating the response to antidepressant drug treatment." (PMID 39050288, 2024). "Elevated serum levels of other circulating cytokines, such as interleukin (IL)-6 and tumour necrosis factor (TNF-α) (depending on the depression subtype), have also been detected during major depression, showing a dose-response relationship with the severity of depression." (PMID 38541828, 2024).
depression (continued). "Furthermore, pro-inflammatory cytokines such as IL-1β and TNF-α have been reported to play an important role in the onset of depression, and an increase in pro-inflammatory cytokines contributes to the development of depression." (PMID 39057075, 2024). "Moreover, the cytokines IL-6, TNF-α, and IL-8 have been suggested as molecules involved in depression, specifically in chronic fatigue and sleep disorders." (PMID 39453274, 2024). "The increase of pro-inflammatory cytokines (interleukin (IL)-1β, IL-6, IL-18, and TNF-α) in individuals with depression may elicit neuroinflammatory processes and peripheral inflammation, mechanisms that, in turn, can contribute to gut microbiota dysbiosis." (PMID 38474387, 2024). "Supplementing 2 g of curcumin per day at the same time as taking antidepressant medication in people aged 31 to 59 years with depression had a positive anti-depressive effect and even a modified effect by reducing inflammatory markers such as IL-1, salivary cortisol levels, TNF-α and BDNF." (PMID 38672750, 2024). "First, TNF-α could activate astrocytes to modulate neuroinflammatory responses in depression and promote neuronal degeneration by binding to TNFR1." (PMID 38710713, 2024). "Elevated TNF-α level can potentially distinguish bipolar disorder from major depressive disorder." (PMID 39283831, 2024). "Pro-inflammatory cytokines such as TNF-α and IL-1β are pivotal in the neuroinflammatory response observed in LPS models, playing critical roles in the pathogenesis of neurodegenerative and psychiatric disorders, including depression and cognitive impairments." (PMID 39459047, 2024). "High levels of plasma or prefrontal cortex TNF-α is associated with suicidal ideation in depression or non-depressed people." (PMID 38459460, 2024). "An increased TNF-α level could distinguish bipolar disorder from major depressive disorder (P < .001)." (PMID 39283831, 2024). "To determine whether treatment with TNF-α affected depression, considering the TNFR1 inducing pro-inflammatory effects, we constructed a GFP adeno-associated viral (AAV) vector carrying a knockdown TNFR1 gene driven by the CMV promoter (AAV-TNFR1)." (PMID 38710713, 2024). "In a meta-analysis IL-6, IL-8 and TNf-α were elevated in the CSF of individuals with depression." (PMID 39526037, 2024). "In addition, XYS reduced the levels of IL-1β, IL-6, and TNF-α and increased the level of IL-10 in the sera of the mice with depression-like behaviors." (PMID 38378622, 2024). "Thus, sensing TNF can be used for diagnosing and guiding the treatment of depression, especially for patients who have undergone cancer therapy." (PMID 39329797, 2024). "Elevated levels of TNF, IL‐6, and IL‐1β in depression may result from dysfunction in the brain's anti‐inflammatory mechanisms, including the HPA axis and noradrenergic innervation." (PMID 38898740, 2024). "Similarly, it has been discussed that patients with severe depression have higher peripheral TNF levels, which also correlate with the disease’s severity." (PMID 38892934, 2024). "Tumor necrosis factor-alpha (TNF-α) can bring about infirmity-like syndromes comparable to IFN-γ, accompanying delirium and hyperthermia, accepted depression, and fatigue, but can further cause vascular discharge, cardiomyopathy, pleura harm, and severe-step protein combination." (PMID 39050096, 2024). "Animal studies demonstrated that prolonged Sb exposure increased levels of inflammatory factors (interleukin-1β (IL-1β), IL-6, and TNF-α) and pro-oxidant substances (glutathione peroxidase, malondialdehyde), indicating that Sb boosts inflammatory responses, closely tied to depression." (PMID 39691784, 2024). "Likewise, heightened levels of IL-1β, IL-6, IL-12, IL-18, TGF-β, and TNF-α are linked to AD, and importantly, patients diagnosed with both AD and depression demonstrate the highest levels of IL-6 and TNF-α in their circulatory system." (PMID 38903903, 2024).
depression (continued). "Some previous studies have described a positive relationship between TNF-alpha and depression." (PMID 38737407, 2024). "One study found that TNF-alpha and cytosolic interleukin (I)-6 transcriptional signaling may be increased in patients with refractory depression, implying that lipid peroxidation may inhibit therapeutic response in depressed patients." (PMID 38802840, 2024). "Similar to TNFα, IL-6 has long been investigated in relation to the pathophysiology of depression." (PMID 39358787, 2024). "Furthermore, it leads to heightened corticosterone levels and triggers activation of the innate immune system, resulting in elevated inflammatory cytokines (such as IL-6, IL-1β, and TNFα), thus impacting the onset of depression." (PMID 38680928, 2024). "Our results showed that chronic stress, inducing depression-like behaviors in mice, led to increased levels of TNF-α, TNFR1, C3, CXCL1, and cleaved-caspase-3, indicating that astrocyte activation and neuronal apoptosis occurred during these depression-like behaviors." (PMID 38710713, 2024). "Only a little data shows slightly reduced TNF-α level in depression." (PMID 38459460, 2024). "The effects of TNFα on depression may be due to its activation of the HPA axis and a subsequent reduction in serotonin (5-HT) metabolism in addition to the vulnerability of the BBB to the inflammatory function of TNFα." (PMID 39358787, 2024). "In a model of LPS-induced depression, fluoxetine (20 mg/kg, i.g.)inhibited glial activation, decreasing levels of pro-inflammatory cytokines such as TNF-α, IL-1β, and IL-6, and increasing levels of the anti-inflammatory cytokine IL-10 in the hippocampus of male C57BL/6J mice." (PMID 38474387, 2024). "Also, by reducing IL-1α, IL-6, and TNF-α expression and suppressing NF-κB activity in the hippocampus, Lacticaseibacillus paracasei NK112 protected against depression caused by Escherichia coli." (PMID 39459643, 2024). "Importantly, increasing the expression of hsa-miR-532-5p in these mice led to a decrease in depression-like behaviors and the suppression of inflammatory markers like IL-6, IL-1β, TNF-α, and MCP-1." (PMID 39451524, 2024). "Upstream signaling events of TNF-α lead to NF-κB pathway activation in the dorsal striatum, inducing the rapid transcription of genes regulating inflammation, cell survival, proliferation, and differentiation, and subsequently depression-like behaviors." (PMID 38791125, 2024). "Quercetin may inhibit the function of TNF-α and other types of cytokines to reduce neuroinflammation and alleviate symptoms of depression." (PMID 39385284, 2024). "Interestingly, these inflammatory mediators are different from the ones previously reported in depression (TNF-α, IL-1β and IL-6)." (PMID 38473935, 2024). "After treatment with interferon and ribavirin, there was positive correlation between depression severity and cytokines including IL-8, IL-10, IL-16, TNF-α, TGF-β and IFN-β in patients with chronic hepatitis C. Both pro- and anti-inflammatory responses were activated." (PMID 38459460, 2024). "TNF-α level may rise at the onset of depression for compensating neuronal disturbances and decrease after antidepressant treatment." (PMID 38459460, 2024). "This is confirmed by our detection of increased serum IL-6, TNF-α, CRH, and CORT levels as well as decreased hippocampal BDNF expression in depression-like mice, these results are both caused by depression and in turn can exacerbate depression." (PMID 39494347, 2024). "Interestingly, while psychiatric side-effects are well known with anti-TNF-α drug treatments, these same drugs can improve depressive symptoms but only in patients suffering from depression with high levels of peripheral inflammatory markers." (PMID 38586283, 2024).
depression (continued). "We also found significant evidence of differential effects by depression and pro-inflammatory cytokines such as IL-1β, IL-6 and TNF-α, in which the effects of D-50 (vs. placebo) were significantly greater among those with depression or elevated plasma concentrations of such cytokines." (PMID 39019875, 2024). "In the context of managing treatment-resistant depression in individuals characterized by elevated baseline inflammatory markers, Infliximab, an anti-TNF-α antibody primarily indicated for autoimmune inflammatory conditions, has demonstrated the capacity to alleviate depressive symptoms." (PMID 39273641, 2024). "In this study, we found that the adverse effects of TNF-α promoting stress-induced depression-like behavior in CUMS mice may involve binding to the TNFR1 to activate astrocytes." (PMID 38710713, 2024). "In addition, TNFα, predict the onset of major depressive disorder over the subsequent months or years in otherwise healthy individuals and intravenous administration of pro-inflammatory agents triggers the appearance of depressive symptoms." (PMID 40656087, 2024). "In addition, there is a certain correlation between depression and serum inflammatory factors such as IL-6, TNF-α, and CRP." (PMID 38698338, 2024). "Additionally, PAMK decreased anxiety/depression-like behaviors and expression of IL-6, IL-1β, TNF-α, and MCP-1 in the hippocampus." (PMID 39599623, 2024). "In the late-life depression, TNF-α contributes to the reduction of serotonin." (PMID 38459460, 2024). "This study highlights elevated TNF‐α levels and reduced hippocampal volume in MCI MDD patients, indicating a potential association between peripheral inflammation and structural brain alterations in depression." (PMID 39236111, 2024). "Moreover, patients diagnosed with depressive disorders have been observed to have increased central and peripheral levels of a number of pro-inflammatory cytokines, mainly tumor necrosis factor α (TNF-α) and interleukins (ILs)." (PMID 38892934, 2024). "Several studies have shown that patients with rheumatic diseases could benefit from TNF-α antagonist (etanercept) treatment for depression." (PMID 37346903, 2023). "By contrast, BV2 cells treated with TNF-α in the presence of NF-κB inhibitor pyrrolidine dithiocarbamate (PDTC) suppressed the expression of CD68 and IL-6 and activity of NF-κB, implying that TNFα controls microglial activation by NF-κB signaling in lupus with depression." (PMID 38164134, 2023). "Studies have primarily assessed whether there is a relationship between the peripheral concentration of pro-inflammatory markers such as c-reactive protein (CRP), interleukin-6 (IL-6) and tumor necrosis factor-α (TNF-α) and the development of depression." (PMID 37928924, 2023). "Also, a recent study from the national Manitoba cohort with prospective data collection showed that presence of anxiety and depression increases the likelihood of anti-TNF discontinuation." (PMID 39132037, 2023). "Moreover, a significant correlation was found between the severity of depression due to MS and increased expression of TNF-α and IFN-γ genes." (PMID 37509005, 2023). "Furthermore, the present study revealed that CORT-induced depression in mice resulted in notable depression symptoms, increased levels of pro-inflammatory factors, including IL-1β and TNF-α, and an increase in NF-κB phosphorylation." (PMID 37954847, 2023). "These investigators revealed that anti-TNF therapy combined with immunomodulatory therapy (azathioprine, 6-mercaptopurine, or methotrexate) reduced both disease activity and symptoms of anxiety/depression in patients with IBD." (PMID 36698151, 2023). "In addition, depression in COPD was linked with increased 24-h overall levels of sputum IL-1 and TNF-α and flattened diurnal salivary cortisol levels." (PMID 37048736, 2023). "Depression was positively correlated to TNF-α on D1 (P=0.009), D3 (P=0.012), and D7 (P=0.032)." (PMID 37878890, 2023).
depression (continued). "Furthermore, we investigated the relationship between pro-inflammatory cytokines and depression by measuring the concentration of TNF-α, IL-6, and IL-1β in mice." (PMID 37173696, 2023). "In a previous study, a correlation was established between depression and elevated levels of proinflammatory cytokines, including interleukins and tumor necrosis factor, as well as increased expression of inflammatory molecules, as measured via acute phase proteins, including the C-reactive protein." (PMID 38137013, 2023). "Furthermore, it has been shown that the serum levels of inflammatory cytokines such as interleukin- 1beta (IL-1β), IL-6, and tumor necrosis factor-alpha (TNF-α) are higher in individuals suffering from depression in compared to healthy people." (PMID 37151621, 2023). "Finally, the vast majority of research that has examined the associations between insomnia, inflammation, and depression, has assessed CRP and circulating levels of IL-6 and TNF." (PMID 36879913, 2023). "In the pain-depression dyad model, we evaluated immobile time, neurotransmitter levels, interleukin-1 (IL-1β) and tumor necrosis factor-α (TNF-α) levels, and the expression of mRNA of brain-derived neurotrophic factor (BDNF) and tryptophan hydroxylase 2 (Tph2)." (PMID 38259687, 2023). "Pro-inflammatory cytokines such as IL-6 and TNF-α were elevated in patients with depression." (PMID 36979303, 2023). "Consistently, the present study showed that MSD increased the expression levels of the proinflammatory factors IL-1β, IL-6, and TNF-α in the hippocampus, which may have contributed to the depression and cognitive dysfunction in the elderly offspring mice." (PMID 37168717, 2023). "In addition, a higher risk of depression has been linked to higher levels of Interferon gamma (IFN-γ), Interleukin 2 (IL-2), TNF-α as pro-inflammatory cytokines, and inflammatory markers as C-reactive protein (CRP)." (PMID 37386551, 2023). "Although evidence about the effect of traditional DMARDs on psychological disorders is contradictory, some studies reported that new biologic DMARDs such as TNF-α antagonists could decrease depression symptoms in patients with RA." (PMID 37346903, 2023). "TNF-α and IL-6 induce the production of indoleamine 2,3 -dioxygenase (IDO), leading to a decrease in tryptophan and the production of tryptophan metabolites, which are associated with depression." (PMID 36860860, 2023). "TNF-α response is an early cell-signaling proinflammatory factor that has been reported at lower levels or without significantly different levels in neurological conditions such as depression." (PMID 37840804, 2023). "Additionally, other pro-inflammatory cytokines showed similar outcomes in depression like IL-1β, TNF- α, and IL-18." (PMID 37957650, 2023). "Indeed, chronic administration of infliximab, a TNFα antagonist, reduces anxiety- and depression-like behavior following chronic stress in rodents." (PMID 37706039, 2023). "The combined therapy could reduce The depression state and the levels of IL-6 and TNF-α, and enhance the cognitive function of patients." (PMID 37273720, 2023). "Treatment through vedolizumab (anti-TNFα therapy) has been seen to improve depression scores." (PMID 37629273, 2023). "Physical activity may promote mental health by decreasing anxiety and depression symptoms by downregulating TNF-α and other inflammation parameters." (PMID 37887970, 2023). "Interleukin 6 plays a role in the development and physiological or somatic consequences of major depression, and the levels of two types of cytokines, namely interleukin 6 and tumor necrosis factor α (TNFα), are significantly higher in patients with major depression." (PMID 37692307, 2023).